ALKBH5 (alkB homolog 5, RNA demethylase)
Diseases named in the same sentence as ALKBH5 in open-access papers (continued):
Sharing a sentence is not in itself a finding about the gene and the disease.
breast cancer (continued). "Thus, ALKBH5 and HIF-1α expression were concordant in all 9 breast-cancer biopsies analyzed." (PMID 27590511, 2016). "Besides, ALKBH5 is upregulated in breast cancer samples compared to noncancerous tissue." (PMID 35063010, 2022). "Because hypoxia-induced ALKBH5 expression is HIF-dependent in breast cancer cell lines and human breast cancers are hypoxic, with a median pO2 of 10 mm Hg (∼1.5% O2), we hypothesized that ALKBH5 and HIF-1α expression should be correlated in breast cancer tissue." (PMID 27590511, 2016). "Under non-hypoxic conditions, ALKBH5 promotes mRNA stability and expression of NANOG by catalyzing m6A demethylation, thus leading to the enrichment of breast cancer stem cells." (PMID 34900723, 2021). "Although all seven breast cancer cell lines displayed BCSC enrichment and increased expression of one or more pluripotency factors in response to hypoxia, neither ALKBH5 nor ZNF217 expression was induced by hypoxia in SUM149 or T47D cells." (PMID 27590511, 2016). "Hypoxia induced ALKBH5 expression in MCF-7, MDA-MB-231, and SUM-159 breast cancer cells, but not in HCC-1954, SUM-149, T47D, or ZR75.1 cells, illustrating the heterogeneous nature of the transcriptional response to hypoxia." (PMID 27590511, 2016). "ALKBH5 belongs to the non-heme Fe(ii)- and α-ketoglutarate (KG)-dependent dioxygenase AlkB family of proteins demethylated NANOG mRNA, and stimulated the expressions of HIF-1α and HIF-2α of breast cancer cells when exposure to hypoxia." (PMID 32500031, 2020).
pancreatic cancer (112 papers, 2019 to 2025). "In pancreatic cancer, the loss of ALKBH5 affects the methylation of lncRNA KCNK15-AS1 and promotes tumor cell migration." (PMID 38798700, 2024). "In pancreatic cancer, low ALKBH5 levels are associated with adverse clinical outcomes, while its overexpression inhibits tumor cell proliferation, migration, invasion, and tumor growth." (PMID 39192357, 2024). "For cancers caused by a deficiency in ALKBH5, such as bladder cancer and pancreatic cancer, the most direct way to restore the expression and function of ALKBH5 is to introduce wild-type ALKBH5 into cancer cells." (PMID 35063010, 2022). "For example, in pancreatic cancer cells, loss of ALKBH5 induces increased methylation of the lncRNA KCNK15-AS1, leading to its downregulation and increased cell migration." (PMID 33461542, 2021). "A retrospective multi-cohort study showed that the m6A eraser ALKBH5 was an independent prognostic factor for pancreatic cancer, and its expression was positively associated with the OS of pancreatic cancer patients." (PMID 34330301, 2021). "Deletion of the RNA demethylase ALKBH5 is associated with the poor clinicopathological and carcinogenesis of pancreatic cancer." (PMID 34489709, 2021). "The results suggested that pancreatic cancer patients with ALKBH5 CNV were associated with worse overall survival and disease-free survival than those with diploid genes." (PMID 34055982, 2021). "After identifying FBXL5, SLC25A28, and SLC25A37 as substrate RNAs of ALKBH5, we further investigated the relevant mechanism associated with pancreatic cancer progression." (PMID 34733841, 2021). "With respect to another type of eraser, ALKBH5, studies have found that silencing of ALKBH5 can significantly increase the proliferation, migration, and invasion of pancreatic cancer cells, and its overexpression will cause the opposite effect." (PMID 34149432, 2021). "High expression of ALKBH5 was significantly associated with low OS in colorectal cancer while it was associated with better survival in stomach and pancreatic cancer." (PMID 32863943, 2020). "On the other hand, the loss of ALKBH5 often indicates a poor prognosis for colon and pancreatic cancers." (PMID 33552994, 2020). "Reduced ALKBH5 levels in pancreatic cancer tissues were identified through various technologies, and survival analysis indicated a significant association between ALKBH5 expression and poor prognosis in patients with pancreatic cancer." (PMID 38856795, 2024). "Emerging evidence has revealed that the aberrant expression of m6A‐associated enzymes, such as ALKBH5, may lead to tumourigenesis, including lung cancer, pancreatic cancer and hepatocellular carcinoma, and these enzymes are promising therapeutic targets." (PMID 36864711, 2023). "And ALKBH5 prevented pancreatic cancer progression by posttranscriptional activation of period circadian regulator 1 (PER1) in an m6A‐YTHDF2‐dependent manner." (PMID 40214031, 2025). "ALKBH5-mediated elevation of DNA-damage-inducible transcript 4 antisense RNA 1 (DDIT4-AS1) sustains pancreatic cancer stem-like properties and reduces chemotherapeutic responsiveness through mTOR pathway activation." (PMID 40986143, 2025). "In pancreatic cancer (PC), ALKBH5 knockdown accelerates tumor development, while its overexpression enhances tumor growth in vivo but inhibits migration, invasion, and proliferation of pancreatic cancer cells in vitro." (PMID 40271153, 2025).
pancreatic cancer (continued). "ALKBH5 can maintain the stemness of pancreatic cancer cells and inhibit their sensitivity to gemcitabine." (PMID 40271153, 2025). "ALKBH5 also contributes to drug resistance in pancreatic cancer by modulating mRNA expression through its influence on m6A modification of long non-coding RNA (DDIT4-AS1)." (PMID 39791162, 2025). "In pancreatic cancer, suppression of ALKBH5 significantly promotes the migration, invasion, and proliferation of pancreatic ductal adenocarcinoma (PDAC) cells both in vitro and in vivo, whereas ALKBH5 overexpression yields the opposite effects." (PMID 40271153, 2025). "Reversely, ALKBH5 acts as a tumor suppressor gene that represses pancreatic cancer progression by posttranscriptional activation of PER120." (PMID 38481816, 2024). "By contrast, ALKBH5 functions as a tumor suppressor in pancreatic cancer (PC), as described by a positive correlation between high ALKBH5 expression and improved survival in PC patients." (PMID 38545555, 2024). "Upregulated HDAC4 stabilizes hypoxia-inducible factor-1α (HIF1α) in hypoxic pancreatic cancer cells, creating a positive feedback loop that increases ALKBH5 expression." (PMID 38856795, 2024). "Whereas in pancreatic cancer, ALKBH5 acts as a tumor suppressor, and its up-regulation can improve the survival rate of pancreatic cancer patients." (PMID 38166832, 2024). "Under hypoxia, the significantly increased transcription and protein levels of ALKBH5 in pancreatic cancer enhance glycolysis and cell migration." (PMID 38856795, 2024). "In pancreatic cancer, ALKBH5 has been shown to directly modulate DDIT4-AS1, promoting the proliferation and metastasis of pancreatic cancer cells by inhibiting mTOR signaling." (PMID 39468015, 2024). "ALKBH5 has emerged as a promising candidate for drug development with its significant tumor-suppressive functions and the ability to sensitize pancreatic cancer cells to chemotherapy." (PMID 38856795, 2024). "Recent reports show that histone deacetylase 4 (HDAC4) regulates HIF-1α protein acetylation and stability and ALKBH5 regulates m6A-modification of HDAC4 transcripts under hypoxic conditions in pancreatic cancer cells." (PMID 38227578, 2024). "Through regulating the Wingless/Integrated (WNT) pathway and reducing WIF-1 RNA methylation, ALKBH5 inhibits the tumorigenicity of pancreatic cancer cells." (PMID 38072944, 2023). "We checked the levels of FTO and ALKBH5 expression in gemcitabine-resistant cells to confirm the function of m6A erasers in controlling gemcitabine chemosensitivity in pancreatic cancer." (PMID 37605223, 2023). "Deletion of Alkbh5 has been shown to aggravate the occurrence and poor clinicopathological features of pancreatic cancers." (PMID 38072944, 2023). "Together, these results found a ALKBH5/HDAC4/HIF1α positive feedback loop for cellular response to hypoxia in pancreatic cancer." (PMID 37149664, 2023). "We also found that HIF1α knockdown strongly decreased the mRNA and protein levels of ALKBH5 in hypoxic pancreatic cancer cells." (PMID 37149664, 2023). "For instance, ALKBH5 overexpresses in pancreatic cancer cell line and regulates RNA stabilities of LC25A28 and SLC25A37 through modulating regulators of iron metabolism and underscores the multifaceted role of m6A in pancreatic cancer." (PMID 36781839, 2023). "A study showed that ALKBH5 overexpression can inhibit the proliferation of pancreatic cancer cells in vitro, whereas ALKBH5 knockdown promoted the progression of pancreatic cancer." (PMID 37771377, 2023).
pancreatic cancer (continued). "Our study also confirmed that overexpressing HIF1α promoted ALKBH5 transcription in pancreatic cancer cells." (PMID 37149664, 2023). "Several studies have reported that the function of m6A methyltransferases in malignancies, as METTL3 accelerates pri-miR221/222 maturation to promote bladder cancer progression, ALKBH5 activates PER1 to inhibit pancreatic cancer progression." (PMID 37807062, 2023). "Our assays also demonstrated that hypoxia-induced HDAC4 enhanced HIF1a protein stability, and overexpressed HIF1a promoted transcription of ALKBH5 in hypoxic pancreatic cancer cells." (PMID 37149664, 2023). "Other studies have revealed a new mechanism by which ALKBH5 methylation lncRNA KCNK15‐AS1 inhibits the movement of pancreatic cancer." (PMID 34850551, 2022). "The role of the m6A demethylase ALKBH5 in pancreatic cancer has also been reported: the mRNA level of m6A in pancreatic cancer tissues is significantly increased due to a decrease in the demethylase ALKBH5." (PMID 35155557, 2022). "ALKBH5 is dysregulated in many tumours, such as hepatocellular cancer, pancreatic cancer and gastric cancer." (PMID 35979628, 2022). "The overexpression of ALKBH5 can sensitise pancreatic cancer to chemotherapy, which is dependent on enhancing the expression of WIF‐1 and activating Wnt signalling." (PMID 35696608, 2022). "Previous studies have demonstrated that ALKBH5 inhibits the proliferation of various cell types, such as human bladder cancer cells, human pancreatic cancer cells, and human hepatocellular carcinoma cells." (PMID 35130626, 2022). "ALKBH5-mediated promotion of tumor proliferation was also reported in hepatocellular carcinoma, pancreatic cancer, and other cancers." (PMID 36566230, 2022). "In pancreatic cancer, ALKBH5-mediated upregulation of DDIT4-AS1 maintains pancreatic cancer stemness and inhibits chemosensitivity through activation of the mTOR pathway." (PMID 36389678, 2022). "In fact, the mitoferrin-1 splice variants detected in these two studies are the same as those detected in a study of ALKBH5 in pancreatic cancer cells." (PMID 36359860, 2022). "ALKBH5 acts as a tumor suppressor in vitro and in vivo in pancreatic cancer and can inhibit its growth and metastasis by targeting PER1." (PMID 35155557, 2022). "ALKBH5 was reported to inhibit pancreatic cancer tumorigenesis by decreasing WIF-1 RNA methylation through mediating Wnt signaling." (PMID 34345203, 2021). "ALKBH5 is also believed to be a novel biomarker and independent prognostic factor in pancreatic cancer and NSCLC." (PMID 35004679, 2021). "Low expression of m6A eraser ALKBH5 was found in a cohort of pancreatic cancer (PC) patients in which both the mRNA and protein levels of ALKBH5 were downregulated in the cancerous tissues compared to the noncancerous pancreatic tissues." (PMID 33814008, 2021). "One research found that YTHDF2 participated in the progression of pancreatic cancer via collaborating with ALKBH5, a pivotal demethylase of m6A." (PMID 33593354, 2021). "Deletion of ALKBH5 is related to poor clinicopathological characteristics and prognosis in pancreatic cancer (PC)." (PMID 34246319, 2021). "Further, ALKBH5 was found to suppress progression in pancreatic cancer and hepatocellular carcinoma." (PMID 34496932, 2021). "As in the case of colorectal cancer, ALKBH5 showed obviously weaker mRNA expression in pancreatic cancer than in the normal tissue." (PMID 34055982, 2021). "For instance, the lncRNA KCNK15-AS1 inhibits the metastasis of pancreatic cancer through ALKBH5 demethylation." (PMID 34288797, 2021).
pancreatic cancer (continued). "ALKBH5 overexpression blocked this pathway by m6A demethylation-mediated upregulation of Wnt inhibitory factor-1 (WIF-1) which in pancreatic cancer was overcome by ALKBH5 downregulation." (PMID 33814008, 2021). "ALKBH5 overexpression repressed pancreatic cancer tumorigenesis by reducing WIF-1 RNA methylation and inactivating Wnt signaling." (PMID 34491904, 2021). "Further study is still needed to illustrate the potential effects of ALKBH5 on the regulation of the downstream genes in pancreatic cancer." (PMID 34055982, 2021). "It has been proved that ALKBH5 inhibited pancreatic cancer motility by demethylating lncRNA KCNK15-AS." (PMID 34330301, 2021). "Previous research showed that demethylase ALKBH5 represses pancreatic cancer progression by up-regulating PER1 expression via m6A-YTHDF2-dependent pathway." (PMID 34916487, 2021). "Taken together, our results reveal that ALKBH5 attenuates pancreatic cancer progression by targeting the regulators of iron metabolism." (PMID 34733841, 2021). "ALKBH5 in pancreatic cancer also has been shown to inhibit tumourigenesis by reducing WAF-1 levels and hindering Wnt signalling activation." (PMID 33461542, 2021). "FTO is involved in the inhibition of EMT in intrahepatic cholangiocarcinoma (ICC), and ALKBH5 impairs the migration and invasion of pancreatic cancer." (PMID 34211849, 2021). "Overexpression of the ALKBH5 inhibits the proliferation, migration and invasion of pancreatic cancer cells in vitro, while knockout of ALKBH5 gene promotes the progress of pancreatic cancer." (PMID 34489709, 2021). "MiR-25-3p targets to inhibit the expression of tumor suppressor PHLPP2, thereby activating AKT-p70S6K oncogene signal and promoting the start and development of pancreatic ductal adenocarcinoma (PDAC); ALKBH5 is down-regulated in pancreatic cancer tissues." (PMID 35070987, 2021). "Our study reveals a previously uncharacterized mechanism of ALKBH5 in protecting against pancreatic cancer through modulating regulators of iron metabolism regulators and expanded our understanding of the association between m6A and iron homeostasis." (PMID 34733841, 2021). "ALKBH5 inhibits the progression of pancreatic cancer through the m6A-YTHDF2-dependent post-transcriptional activation of PER1." (PMID 34246319, 2021). "The eraser ALKBH5 prevents pancreatic cancer progression by posttranscriptional activation of PER1 through m6A abolishment, decreasing WIF-1 RNA methylation and mediating Wnt signaling." (PMID 35047414, 2021). "Intriguingly, out of the eight RNA m6A regulators analyzed in this study, only ALKBH5 served as an independent favorable prognostic factor, suggesting its massive impact in the progression of pancreatic cancer." (PMID 34733841, 2021). "In TME, ALKBH5 overexpression can inhibit pancreatic cancer by decreasing the level of m6A RNA modification of WIF-1, blocking the activation of Wnt signaling, and increasing the sensitivity of pancreatic cancer cells to drugs." (PMID 34660577, 2021). "Another study showed that demethylase ALKBH5 suppressed pancreatic cancer progression by post-transcriptional activation of PER1 in an m6A-YTHDF2-dependent manner." (PMID 34239358, 2021). "On the other hand, other researchers indicated the opposite conclusions about the expression level and the role of ALKBH5 in pancreatic cancer, colon cancer and clear cell renal cell carcinoma." (PMID 32742194, 2020). "For instance, m6A demethylase ALKBH5 was reported to induce gastric cancer metastasis by demethylating lncRNA NEAT1, whereas an earlier study showed an important role for ALKBH5 in inhibiting pancreatic cancer progression." (PMID 32218194, 2020). "In pancreatic cancer, downregulated ALKBH5 predicts poor prognosis and knockdown of ALKBH5 markedly facilitates tumor growth and metastasis." (PMID 33015074, 2020).